AGRP (agouti related neuropeptide)
Diseases named in the same sentence as AGRP in open-access papers (continued):
Sharing a sentence is not in itself a finding about the gene and the disease.
Obesity (continued). "In this context, the identification of ARC neuromediators other than those released by the POMC/CART and NPY/AgRP/GABA neurons that could relay the catabolic message of leptin via the melanocortin system, appeared justified in our understanding of the pathophysiology of obesity." (PMID 28690493, 2017). "It is also possible that AgRP dendrites have lost spine expression due to lack of LepRb expression in neurons (except AgRP neurons) in the Leprbdb/db; Agrp-ires-cre; HA-Leprb flox mice, or indirectly because of the obesity or other abnormalities of these animals." (PMID 24204898, 2013). "We previously reported that while there was remarkable anti-obesity phenotype in HFD-fed Syn1-Cre; Ghsrf/f and AgRP-cre; Ghsrf/f mice, the total daily food intake was no different." (PMID 35204795, 2022). "Our findings revealed the interactive role of DQI-I in reducing obesity related metabolic profile including BMI, FM and FSG and AgRP in AA genotype of CARTPT; no human study is available evaluating the relationship between AgRP and CART gene polymorphisms." (PMID 31918705, 2020). "In contrast, ablation of mitofusins in NPY/AgRP neurons disrupts mitochondrial fusion without inducing ER stress and alleviates HFD-induced obesity." (PMID 28270795, 2017). "Further, obesity leads to aberrant signaling in the ARC and other hypothalamic structures, so it was not surprising to quantify low AgRP expression whilst rats continue to over-consume." (PMID 36817590, 2023). "In a single-cell transcriptomics analysis of the hypothalamus, it has been shown that, in long-term diet-induced obesity, the expression of CREB is reduced in AgRP/NPY neurons; however, no previous study has evaluated the impact of the short-term consumption of an HFD on Pomc CREB." (PMID 35805082, 2022). "In addition, while chronic inhibition of AGRP neurons fails to alter food intake and body weight in ob/ob mice, chronic inactivation of all GABAergic neurons in the ARH largely ameliorates hyperphagia, hyperglycemia and obesity in mice lacking leptin." (PMID 38027481, 2023). "Here, we report that in adult mouse AGRP neurons, CRISPR-mediated genetic ablation of Tet3, not previously known to be involved in central control of appetite and metabolism, induced hyperphagia, obesity, and diabetes, in addition to a reduction of stress-like behaviors." (PMID 36189793, 2022).
Anorexia (37 papers, 2009 to 2026). Lack of desire to eat (loss of appetite). "Animals deficient for POMC are obese, while ablation of AgRP neurons in adult mice leads to anorexia and leanness, highlighting the importance of POMC and AgRP neurons in regulating energy homeostasis." (PMID 38027481, 2023). "Conversely, ablation of AgRP neurons in adult mice causes acute anorexia whereas mice that overexpress AgRP become obese." (PMID 22479599, 2012). "Taken together, the results strongly suggest that the hypoactivity of AgRP hypothalamic neurons may underlie some of the symptoms of anorexia." (PMID 39872404, 2025). "One of the components influencing weight loss during immobilization stress, apparently, is the increased expression kinetics of anorexigenic (POMC and CART) and orexigenic (NPY and AgRP) peptides and, as a result, anorexia caused by a violation of the homeostatic circuit." (PMID 36558137, 2022). "Moreover, they showed that GABA replacement in the PBN prevented anorexia and body weight loss after AgRP neuron ablation." (PMID 23293630, 2012). "Optogenetic stimulation of GLP-1R–expressing TRH-positive neurons in the ARC also suppressed feeding via AgRP neuron inhibition, and AgRP neuron stimulation partially overcame Ex-4 or TRH-neuron stimulation–induced anorexia." (PMID 41542773, 2026). "For instance, in the hypothalamus, a brain region that controls food intake, TNFα inhibits orexigenic AgRP neurons and activates anorexigenic proopiomelanocortin (POMC) neurons, promoting inflammation-associated anorexia." (PMID 39958993, 2025). "Thus, AgRP neuron inhibition likely contributes to incretin analog-induced appetite suppression, though future studies will be required to show causality and exclude the possibility that AgRP neuron stimulation induces food intake via a mechanism independent from incretin-induced anorexia." (PMID 40857106, 2025). "The association between eating disorders and occlusal disharmony has been shown, and individuals with anorexia display perturbation of cognitive function and elevated plasma AgRP levels." (PMID 37168929, 2023). "In this study, AgRP neuropeptide in AgRP neurons was demonstrated to play a key role in the transition from the anorexia stage (plant protein feeding for 3 weeks) to the adaptation stage (feeding for 4–8 weeks)." (PMID 36387900, 2022). "Both NPY/AgRP and POMC are important downstream targets of insulin, and one of the core roles of insulin is to produce anorexia by suppressing the NPY/AgRP neurons and stimulating POMC neurons." (PMID 33868169, 2021). "In the mechanisms of anorexia in cancer, orexigenic peptide, agouti-related protein (AgRP) and ghrelin have been observed to decrease pro-inflammatory cytokines and to increase body weight, food intake, and muscle mass in CC." (PMID 33557173, 2021). "In this sense, our findings indicate that the acute effects of TNF-α and IL1-β on AgRP-producing neurons likely contributes to the inflammation-induced anorexia since both cytokines inhibit the activity of 35–42% of AgRP neurons recorded." (PMID 33255553, 2020). "We conclude that AgRP expression remains sensitive to the level of energy stores during natural anorexias, which is of adaptive advantage, although its normal orexigenic effects are over‐ridden by inhibitory signals." (PMID 26017156, 2015). "Our in vivo results suggest that CTRP13 and AgRP form a neural feedback loop to modulate food intake and that this feedback mechanism is disrupted in an activity-based anorexia (ABA) mouse model." (PMID 23638159, 2013). "Although the methods and the results differed somewhat, there was agreement that acute depletion of AgRP neurons in the adult mouse leads to life-threatening anorexia." (PMID 23293630, 2012). "For example, MC-4 receptor blockade through the central administration of AgRP or the MC-3/4 antagonist SHU-9119 increased food intake in models of cancer-induced anorexia." (PMID 19295909, 2009).
Anorexia (continued). "Our data showing downregulated AgRP in control animals indicate aversion-induced anorexia." (PMID 40004532, 2025). "The central mechanisms involving AgRP for anorexia in humans remain to be clarified." (PMID 39872404, 2025). "In addition, NPY appears to contribute to insulin resistance induced by acute stimulation of AgRP neurons, and GABA release from AgRP neurons has been shown to inhibit stress-activated, anorexia-inducing neurons located in the parabrachial nucleus." (PMID 40371641, 2025). "Recent reports demonstrate that acute access to HFD rapidly alters the activity of hypothalamic AgRP neurons, resulting in a de‐valuation of the regular chow diet, such that acute anorexia develops when animals are switched back from an HFD to a regular chow diet." (PMID 39718394, 2025). "Interestingly, females with anorexia have been found to have elevated AgRP levels in their plasma, perhaps consistent with a role for AgRP in regulating fat mobilization peripherally in the setting of caloric restriction." (PMID 39872404, 2025). "In other words, AgRP neurons can regulate both food intake and energy expenditure, but a compensatory anorexia (due to decreased energy expenditure) may develop over time to mask increased food intake." (PMID 37594983, 2023). "Suppression of AgRP signaling reverses the decline in cognitive function in a mouse anorexia model." (PMID 37168929, 2023). "Upregulated hypothalamic AgRP is associated with significantly lower NOR test scores in mouse anorexia models." (PMID 37168929, 2023). "Nevertheless, studies that identified melanocortin-independent processes observed relative weight differences between treatment groups (e.g., activity-based anorexia, AgRP neuron ablation-induced anorexia, xenin-induced anorexia, histamine-induced anorexia, and cannabinoid-induced anorexia)." (PMID 35742824, 2022). "Recent studies suggest that tumor necrosis factor α and interleukin 1β, especially in AgRP-producing neurons, might contribute to inflammation-induced anorexia during acute inflammatory conditions." (PMID 34840970, 2021). "In addition, genetic models of anorexia suggest that the disruption of NPY/AgRP signaling is partially due to axonal transport dysfunction." (PMID 34899611, 2021). "Our findings indicate that the effect of TNF-α and IL-1β, especially on the activity of AgRP-producing neurons, may contribute to inflammation-induced anorexia observed during acute inflammatory conditions." (PMID 33255553, 2020). "Furthermore, a previous study showed that patients with acute anorexia nervosa had higher AgRP levels than those of healthy controls, but the AgRP levels of weight-restored anorexia patients were similar to those of healthy controls." (PMID 26758700, 2016). "In the limited number of studies where AgRP/NPY or POMC/CART have been measured in mammalian models of stress that result in anorexia, there is some evidence for increased expression of the orexigenic peptide genes but the significance of this finding is uncertain." (PMID 26017156, 2015). "Thus, the increase of DVC AgRP gene expression just after the termination of stress up to 24 h before POMC gene expression suggests that AgRP system drive the expression of the POMC to attenuate the ongoing established anorexia state." (PMID 25100947, 2014). "The AgRP expression pattern is similar to NPY, as its mRNA expression increases but secretion decreases in both acute and chronic inflammatory anorexia models." (PMID 34899611, 2021). "Similarly to our findings, in different models of acute and chronic inflammation-induced anorexia, increased mRNA expression of NPY and AgRP has been observed in the hypothalamus or ARC." (PMID 20953376, 2010). "Patients with anorexia do not eat even when AgRP is activated." (PMID 37168929, 2023).
Anorexia (continued). "Moreover, in our previous reports, we demonstrated that the midsegment region of Nesfatin-1 was responsible for inducing anorexia in vivo and showed a high similarity to AgRP rather than alpha-MSH." (PMID 23236405, 2012). "Our previous study showed that AgRP, and not neuropeptide Y (NPY) is the principal protein molecule that correlates well with feeding behavior in Japanese seabass from anorexia to adaptation." (PMID 36387900, 2022).
Anxiety (29 papers, 2018 to 2025). Intense feelings of nervousness, tension, or panic often arise in response to interpersonal stresses. "AgRP neurons have also been implicated in circuitry controlling non-feeding behavior, including those associated with reward, anxiety and compulsive disorders, more particularly in anorexia nervosa." (PMID 39611656, 2024). "In the current study, we used CRS model and chemogenic strategy to investigate the possible involvement of AgRP neurons in stress-induced anxiety and colitis susceptibility." (PMID 36641530, 2023). "Collectively, these results indicate that inhibition of AgRP neurons mimics stress-induced anxiety-like behaviors and colitis susceptibility." (PMID 36641530, 2023). "Taken together, these results reveal critical roles of hypothalamic AgRP neuron-derived c-Jun in orchestrating stress-induced anxiety and colitis susceptibility." (PMID 36641530, 2023). "Consistently, chemogenic activation or inhibition of AgRP neurons reverses or mimics CRS-induced increase of anxiety-like behaviors and colitis susceptibility, respectively." (PMID 36641530, 2023). "These AgRp gene expression associations are indicative of a beneficial involvement of this neuropeptide on both depression and anxiety measures." (PMID 30233288, 2018). "Overall, the linear regression models pointed to AgRp gene expression associations indicative of a beneficial involvement of this neuropeptide on both depression and anxiety measures." (PMID 30233288, 2018). "Interestingly, stereotypic behaviours induced by AgRP neurons are also associated with decreased anxiety." (PMID 40656109, 2024). "The present results add relevant information to the understanding of the influence of hypothalamic neuropeptides on nonfood-associated behaviors, indicating a possible involvement of AgRP on emotional disruption mechanisms leading to the anxiety and depression states observed after menopause." (PMID 30233288, 2018). "Recent work also suggests that AgRP neurons are activated by emotional stimuli and are involved in anxiety-like behaviours in mice." (PMID 41354852, 2025). "The optogenetic activation of AgRP neurons or their axon terminals within the bed nucleus of stria terminalis (a part of the extended amygdala involved in the regulation of stress, anxiety and feeding) induced temporal discounting in sated mice." (PMID 40656109, 2024). "In a conditioned place preference test, mice undergoing repeated exposure to a stressor, and displaying anxiety-prone phenotypes, developed a preference for starvation-like states produced by the optogenetic stimulation of AgRP neurons." (PMID 40656109, 2024). "In summary, our present findings revealed that AgRP neuronal activity in the ARC is an important link between anxiety-like behavior and intestinal inflammation." (PMID 36641530, 2023). "Although some recent studies have shown that AgRP neurons are involved in chronic unpredictable stress mediated depression-related behaviors and engaged in high-fat diet-induced anxiety and depression." (PMID 36641530, 2023). "Here, we show that hypothalamic agouti-related protein (AgRP) neuronal activity is suppressed under chronic restraint stress (CRS), a condition known to increase anxiety and colitis susceptibility." (PMID 36641530, 2023). "AgRP neurons were shown to regulate anxiety level, but our OFT results demonstrated similar levels of anxiety regardless of genotypes, based on their comparable preference to the center zone and the outer zone in the chamber." (PMID 37594983, 2023). "Specifically, activation of AgRP neurons reduces behavioral signs of anxiety and increases motivation and explorative behaviors." (PMID 39872512, 2023). "Collectively, our results suggest that the anxiety-depressive responses are mediated by HFD-induced desensitization of AgRP neurons." (PMID 33767348, 2021).
Anxiety (continued). "Chronic treatment with a high-fat diet (HFD) significantly blunts the hyperexcitability of AgRP neurons in response to not only hunger but also anxiety and depression-like stimuli." (PMID 33767348, 2021). "GABAergic projections from AgRP neurons to the melanocortin 4 receptor (MC4R) neurons located in the dBNST modulates high-fat diet (HFD)-induced anxiety and depression-like responses." (PMID 33767348, 2021). "The results of this reduction in AgRP enhancer methylation was an increase in AgRP gene expression and an increase in anxiety and depression-like behavior in mice subjected to maternal separation." (PMID 33113946, 2020). "For example, AgRP activation in presence of food drives food intake, whereas when food is not available it drives other motivated goal-directed behaviors and reduces anxiety-like behaviors." (PMID 31998738, 2019). "For example, a diet rich in refined carbohydrates facilitated anxiety and depressive-like behaviors after stress in mice, while a high-fat diet desensitizes the output of hypothalamic AgRP neurons, leading to dysregulation of behavior indicative of anxiety and depression." (PMID 39905823, 2025). "Thus, AgRP neurons drive input-specific synaptic plasticity, enabling a selective shift in hunger and anxiety signaling during starvation through NPY." (PMID 38937485, 2024). "AgRP neurons have been reported to modulate fasting-induced anxiolytic effects, suggesting that decreased AgRP-expressing neurons in WD-fed WT mice might increase anxiety-like phenotypes." (PMID 37926812, 2023). "Several lines of evidence suggest that those neuropeptides, which are increased by hunger (NPY and AgRP), also reduce fear and anxiety, while others released upon refeeding and in particular during states of satiety are predominantly anxiogenic (α‐MSH, CRH, and CCK)." (PMID 31271235, 2019). "We next tested the potential for AgRP neurons to affect anxiety in fed mice." (PMID 30850579, 2019). "The anxiety index presented an inverse correlation with hippocampal AgRP expression (p = 0.004)." (PMID 30233288, 2018). "Agouti-related protein (AgRP)-expressing neurons localised exclusively to the arcuate nucleus (ARC) of the hypothalamus are key modulators of body weight regulation and food seeking behaviour, and they have recently been implicated in anxiety- and anhedonic-like processes." (PMID 41354852, 2025). "Furthermore, in the last decade, AgRP neurons have been associated with neuronal circuits of nonfeeding behavior, including those related to reward, anxiety, and compulsive behavior." (PMID 37994388, 2024). "Gene expression analysis of feeding-related genes (AgRP, NPY, OXT) and those involved in regulating stress and anxiety (DOR and MC3R) were differentially regulated in the VPA rats." (PMID 40004532, 2025). "As a means to investigate anxiety-like behaviour in mice, we employed the EPM at 17-weeks post-injection in AgRP-Cre mice." (PMID 41354852, 2025). "Both agouti-related peptide (AgRP) and α-melanocyte stimulating hormone (α-MSH) regulate appetite, energy homeostasis, and anxiety-like behavior." (PMID 30655577, 2019). "Notably, feeding-related genes (AgRP, NPY, OXT) and those involved in regulating stress and anxiety (DOR and MC3R) were differentially regulated in the VPA rats." (PMID 40004532, 2025). "Although GHSRs are co-expressed on >90% of NPY/AgRP neurons in the ARC, our discovery demonstrates a specific role for GHSRs in the OB, independent from AgRP neurons in foraging and anxiety-like behavior but not food consumption." (PMID 39236785, 2024). "As predicted, stimulation of AgRP neurons (as shown by the increased c-Fos staining and food intake) reversed CRS-induced anxiety-like behaviors with an increase in both center time duration and center distance in the OF test, and an increase in time and entries into the open arms in the EPM test." (PMID 36641530, 2023).